PGR (progesterone receptor)
Diseases named in the same sentence as PGR in open-access papers (continued):
Sharing a sentence is not in itself a finding about the gene and the disease.
breast cancer (continued). "The molecular chaperone αB-crystallin is expressed in estrogen receptor, progesterone receptor and human epidermal growth factor receptor-2 ‘triple-negative’ breast carcinomas and promotes brain and lung metastasis." (PMID 27656679, 2015). "The level of clusterin expression correlated with the level of estrogen and progesterone receptor expression, tumor size, and lymph node metastasis in breast carcinoma." (PMID 26293319, 2015). "In this study, we aimed to assess the clinicopathologic features, natural history, and outcomes of ER-/PgR+ breast carcinomas and compared these to ER+ and ER-/PgR- tumors, using a retrospectively collected individual patient dataset." (PMID 26161666, 2015). "Nevertheless, the application of a PGR blocker decreased PGR expression in canine mammary carcinoma cells and reduced cell proliferation in vivo and cell viability in vitro." (PMID 26370564, 2015). "The most commonly used biomarkers to predict the response of breast cancer patients to therapy are the oestrogen receptor (ER), progesterone receptor (PgR), and human epidermal growth factor receptor 2 (HER2)." (PMID 24460909, 2014). "Determination of hormone receptor (estrogen receptor and progesterone receptor) and human epidermal growth factor receptor 2 status in the primary tumor is clinically relevant to define breast cancer subtypes, clinical outcome, and the choice of therapy." (PMID 25032257, 2014). "Often, breast cancers are characterized by their expression of hormone receptors (estrogen receptor, ER; progesterone receptor, PR; or human epidermal growth factor receptor 2, HER2)." (PMID 24885022, 2014). "TNBC are defined as negative for expression of three genes, estrogen receptor (ESR), progesterone receptor (PR) and Her2 gene, and account for 15-20% of breast cancer types." (PMID 25100201, 2014). "Breast cancer is essentially categorized into four subtypes depending on the expression of ER, PgR, HER2, and Ki67." (PMID 25055938, 2014). "TNBC lacks the three important therapeutic markers for clinical regimens of patients with breast cancer: estrogen receptor (ER), progesterone receptor (PR) and human epidermal growth factor receptor 2 (HER2)." (PMID 24731479, 2014). "Among cancers of the breast, expression profiling of miRNAs shows correlations between miRNA expression and receptor status for estrogen receptor (ER), progesterone receptor (PgR), and V-Erb-B2 avian erythroblastic leukemia viral oncogene homolog 2 (HER2/Nue)." (PMID 25352952, 2014). "Further, cadmium has been shown to induce progesterone receptor (PGR) levels in breast cancer cells, the induction being blocked by anti-estrogen." (PMID 24963789, 2014). "In breast cancer, more than 70%–80% of tumors express the ER or progesterone receptor (PR), and therapies designed to neutralize their function have shown clinical benefit." (PMID 24779793, 2014). "Experimental studies in human breast cancer suggest that the differential expression of progesterone receptor isoforms has implications for hormone therapy responsiveness." (PMID 25515784, 2014). "Approximately 75% of breast cancers express estrogen receptor alpha (ERα) and/or progesterone receptor and these receptors are markers for tumor dependence on estrogen." (PMID 25070479, 2014). "Among the genes retained for analysis, we focused our attention on three that are clinically relevant for breast cancer: ER, PgR, and HER2." (PMID 25412710, 2014). "Letrozole is also more effective than tamoxifen as a preoperative treatment in postmenopausal patients with ER- and/or Progesterone Receptor (PgR)-positive primary breast cancer, although the response rate of 55% is suboptimal." (PMID 25421542, 2014). "Genomic data obtained through the Breast Cancer Gene Expression Miner v3.0 was analyzed for mTOR signaling components (Rictor, Raptor, and Rheb), ERα, and PgR." (PMID 25283550, 2014).
breast cancer (continued). "All breast cancer tissues used for isolation of primary cultures of fibroblasts in this study were of luminal subtype and positive for estrogen receptor and/or progesterone receptor." (PMID 25512109, 2014). "Breast cancer can be classified into different subgroups by the expression of estrogen receptor (ER), progesterone receptor (PR) and human epidermal growth factor receptor 2 (HER2)." (PMID 25228280, 2014). "In human breast cancer, oestrogen receptor (ER), progesterone receptor (PR), and human epidermal growth factor receptor 2 (HER2) are well-established prognostic and predictive markers, and testing for them is now considered standard of care." (PMID 24967588, 2014). "In our study, RNA-Seq showed high correlation with microarrays when measuring clinically relevant genes in breast cancer (i.e., ER, PgR, and HER2)." (PMID 25412710, 2014). "The need for all these data comes from reported breast cancer studies that suggested that PgR expression in cells with ER depends on estrogen exposure during previous days." (PMID 24917206, 2014). "We have also examined the influences of ER, PgR and HER-2 receptors status individually on breast cancer metabolism and explored the metabolite profiles associated with HER-2 overexpression." (PMID 25495193, 2014). "Breast cancers are divided into subgroups and subtypes based on the expression of three cell surface receptors: estrogen receptor (ER), progesterone receptor (PR) and human epidermal growth factor receptor 2(HER2)." (PMID 25360516, 2014). "Most breast cancers (60%) express oestrogen receptor (ER) or progesterone receptor (PR) and are responsive to estrogens for growth and proliferation." (PMID 24795759, 2014). "Further, several analyses based on unselected breast cancer cohorts showed that AR expression is related with ERα and PgR immunostaining as well as a marker of low grade differentiated disease." (PMID 24978437, 2014). "Hormone receptor positive (HR+) breast cancer (defined as estrogen receptor [ER] and/or progesterone receptor expressing tumors) accounts for 60–70% of breast cancers." (PMID 24464780, 2014). "These interactions often lead to post-translational modifications to the progesterone receptor that can dramatically alter receptor function, both in the normal mammary gland and in breast cancer." (PMID 24552158, 2014). "This is particularly important because interlaboratory variations in the evaluation of ER, PgR and Ki-67 expression levels can impact the molecular classification of breast cancer when based on fixed threshold values." (PMID 24951027, 2014). "The association between the expression of each one of these markers with the classical breast cancer prognostic factors as well as with the molecular subtypes and biomarkers ER, PgR, HER2 and Ki67 was evaluated." (PMID 25269858, 2014). "The most commonly diagnosed breast cancer subtypes are luminal A and B tumors, together defined as the ER-positive (ER+) and progesterone receptor-positive (PgR+) tumors." (PMID 24765135, 2014). "It is well established that breast cancer subtypes (as defined by estrogen receptor, progesterone receptor, and her-2 expression) correlate with LR rates, with the highest rates in the estrogen receptor negative subtypes." (PMID 24673853, 2014). "Patients with ‘triple-negative’ breast cancer, referring to absence in the expression of estrogen receptor (ER), progesterone receptor (PR) and human epidermal growth factor receptor 2 (HER2), are insensitive to hormonal therapy or HER2-targeted agents." (PMID 25056574, 2014). "On the other hand, P-REX1 levels are low in basal-like breast cancer, a subtype with high abundance of triple-negative (estrogen receptor (ER)-, progesterone receptor (PR)-, and human epidermal growth factor receptor (HER2)-negative) tumors." (PMID 25248717, 2014).
breast cancer (continued). "We suggest this result relates to a decrease in tamoxifen sensitivity which potentially results from the altered levels of estrogen receptor (ER) and progesterone receptor (PgR) observed upon YAP1 downregulation in the luminal breast cancer cell line T47D." (PMID 24559095, 2014). "The AKT/mammalian target of rapamycin (mTOR) signaling pathway is regulated by 17α-estradiol (E2) signaling and mediates E2-induced proliferation and progesterone receptor (PgR) expression in breast cancer." (PMID 25283550, 2014). "In breast cancers, androgen receptor (AR) is more widely expressed than estrogen receptor alpha (ER) or progesterone receptor (PR), and AR has recently emerged as a useful marker for the further refinement of breast cancer subtype classification." (PMID 24451109, 2014). "It is noteworthy that upregulated expression of mPR has been observed in breast cancer biopsies and subsequent investigation further confirmed the expression of mPR in biopsies of classic progesterone receptor null breast cancer." (PMID 25257522, 2014). "The resulting changes in the expression level of YT521 influenced the splicing of such cancer-associated genes as BRCA2 (breast cancer 2) and PGR (progesterone receptor)." (PMID 25551597, 2014). "Immunohistochemistry markers of favorable prognosis of breast cancer include only ERα, PgR, Bcl-2 and E-cadherin." (PMID 24824621, 2014). "Filtration of blood and subsequent on-filter fixation/staining of the enriched CTCs with Alexa488-EpCAM and PE-CD45 antibody mixture or other labeled antibodies such as HER2 and ER/PgR in cases of breast cancer took 20 min and 45 min, respectively." (PMID 24523941, 2014). "Breast cancer subtypes are defined using the expression levels of key genes such as estrogen receptor (ER), progesterone receptor (PR), and erbB-2 (HER-2/neu)." (PMID 25080362, 2014). "Estrogen receptor (ER) status is an important predictive and prognostic factor in breast cancer, and determination of ER and progesterone receptor (PR) status of patients with breast carcinoma is now standard practice." (PMID 24761803, 2014). "Recently, hormone receptor tests have been widely used as part of pathologic examinations for breast cancer, including estrogen receptor (ER) and progesterone receptor (PR) tests." (PMID 25036532, 2014). "Breast cancer in men is relatively rare, and most breast cancers in men are estrogen receptor/progesterone receptor positive." (PMID 25539790, 2014). "Triple-negative breast cancer (TNBC) is a highly aggressive type of breast cancer and refers to tumors that lack expressions of estrogen receptor (ER), progesterone receptor (PR), and human epidermal growth factor receptor 2 (HER2) genes." (PMID 24982892, 2014). "From among female patients aged 30 years and over admitted to a single hospital in Japan between 1997 and 2011, 1,263 breast cancer cases (672 ER+/PgR+, 158 ER+/PgR-, 22 ER-/PgR+, 308 ER-/PgR- and 103 missing) and 3,160 controls were selected." (PMID 24516791, 2014). "The classical breast cancer subtypes are based on assessment of clinical and pathological factors, for example ER, progesterone receptor (PR), or HER2 status, tumor grade, tumor size, and the presence or absence of lymph node metastasis." (PMID 24829621, 2014). "For breast cancer, we considered factors including patient age, lymph node status, histological grade, tumor size, estrogen receptor (ER) status, and progesterone receptor (PR) status." (PMID 25333947, 2014). "We find that RUNX2 is overexpressed in a particular subset of breast cancers that are oestrogen receptor (ER)/progesterone receptor (PR)/HER2-negative, and that high expression of RUNX2 is associated with poorer patient survival." (PMID 24626992, 2014). "As reported in the literature, ER is expressed in about 70–75% of invasive breast cancer, and about 50% of breast cancer expresses the progesterone receptor (PR)." (PMID 24864130, 2014).
breast cancer (continued). "Immunohistochemical (IHC) labelling at diagnosis has identified approximately two thirds of canine mammary carcinomas as progesterone receptor (PR) positive." (PMID 25515784, 2014). "Expression of PTEN was found to negatively correlate with the tumor size, the pathological stage and the expression of the estrogen receptor (ER) and the progesterone receptor (PR) in breast cancer." (PMID 23946797, 2013). "Progesterone receptor (PR) is crucial for the growth of breast cancer, and its level is regulated by ER." (PMID 23533377, 2013). "The diagnosis of breast cancers were made from core needle biopsy, and the items investigated were histological type, nuclear grade, ER (6 F11, Ventana), PgR (16, Ventana), and HER2 overexpression (CB11, Ventana)." (PMID 23875131, 2013). "Previous immunohistochemistry reports had suggested that breast cancer tumors in Africans were estrogen or progesterone receptor poor." (PMID 24354443, 2013). "Currently it is established that Her-2 (human epidermal growth factor receptor-2), Estrogen Receptor (ER), and Progesterone Receptor (PR) are the most commonly used biomarkers and therapeutic targets in breast cancer patients." (PMID 24363939, 2013). "One case report demonstrated that expression levels of the progesterone receptor (PR) in estrogen receptor (ER)-positive breast cancer cells correlated positively with the responsiveness to tamoxifen, and with the prognosis." (PMID 23805070, 2013). "The second case is a 65 year old female diagnosed with stage I, estrogen receptor (ER)/progesterone receptor (PR) positive breast cancer 3 years prior to our evaluation in the clinic." (PMID 23626575, 2013). "Hormone therapy is recommended in breast cancers that express estrogen receptor alpha (ERα) and/or progesterone receptor (PR)." (PMID 23339407, 2013). "The management and prognosis of breast cancer are largely determined by the expression status of estrogen receptor (ER), progesterone receptor (PR), and human epidermal growth factor receptor 2 (HER2) of the tumor." (PMID 23437271, 2013). "Since ER, PgR and HER2 expression levels can change in metastatic lesions in patients with breast cancer and lead to drug resistance, a biopsy of suspected metastatic lesions is recommended in these patients for the analysis of ER, PgR and HER2 expression." (PMID 23196318, 2013). "Regarding to breast cancer, NPC2 up-regulation is associated with estrogen receptor (-), progesterone receptor (-) and human epidermal growth factor receptor (+)." (PMID 24147030, 2013). "Among 60 breast cancer cases having ER and PgR status data, the sensitivity of US alone was comparable between ER or PgR positive and negative patients." (PMID 23961381, 2013). "Two thirds of breast cancer cases express estrogen (ER) and/or progesterone receptors (PgR); positivity of estrogen or progesterone receptors in breast cancer has been related to the efficacy of tamoxifen, as well as AIs." (PMID 24065098, 2013). "Expression of ER and PGR is a routinely investigated indicator of endocrine therapy success in breast cancer and a modest, but significantly better overall survival of anti-estrogen receptor therapy has been documented." (PMID 23497154, 2013). "Six breast cancer datasets were also used to test the robustness of the progesterone receptor (PGR) signature." (PMID 24058887, 2013). "The American Society of Clinical Oncology and the College of American Pathologists (ASCO/CAP) recently published guideline recommendations for IHC testing of ER and PgR in breast cancer." (PMID 23972025, 2013). "In a genome-wide analysis, progesterone receptor was among the least variable genes in ER- breast cancer." (PMID 23971947, 2013).
breast cancer (continued). "Premenopausal women with estrogen receptor (ER)-positive and/or progesterone-receptor positive, advanced or recurrent breast cancer refractory to an LH-RH analogue plus TAM received goserelin (GOS) in conjunction with anastrozole (ANA)." (PMID 23446822, 2013). "The growth of many breast cancers is hormone-dependent, with estrogen receptor (ER) and/or progesterone receptor (PgR) expression a prerequisite for responsiveness to endocrine therapy." (PMID 23972025, 2013). "Breast cancers are commonly divided into subgroups based on the expression of three cell surface receptors: estrogen receptor (ER), progesterone receptor (PR), and HER2." (PMID 23667446, 2013). "For example, BRCA1 can inhibit progesterone receptor (PR) activity in the PR-positive human breast cancer cell line T47D and repress estrogen receptor-alpha activity in MCF-7 cells." (PMID 24321281, 2013). "High cyclin D1 expression statistically significantly correlated with lower tumor grade, estrogen and progesterone receptor positivity and lower proliferation activity in breast tumors and increased breast cancer-specific survival and overall survival." (PMID 23336272, 2013). "ER and progesterone receptor (PgR) status provides the index for sensitivity to endocrine treatment; therefore, it is the most important biomarker in breast cancer." (PMID 24649257, 2013). "Hormone receptors (HR), estrogen receptor (ER) and progesterone receptor (PgR), play important roles in breast cancer development, progression and response to therapy." (PMID 23368410, 2013). "Estrogen Receptor α (ERα) and progesterone receptor (PR) expression in male breast cancer is present in around 90% of patients, which makes them eligible for adjuvant therapy using tamoxifen and aromatase inhibitors." (PMID 23308200, 2013). "Cyclin D1 was statistically significantly correlated with estrogen and progesterone receptor positivity, a lower tumor grade and lower proliferation activity, that is, with breast cancers that have a good prognosis." (PMID 23336272, 2013). "Upregulation of the insulin-like growth factor/PI3K/AKT/mTOR pathway is one suggested mechanism behind PgR downregulation in breast cancer, despite a functional ER." (PMID 24131622, 2013). "Women diagnosed with estrogen receptor/progesterone receptor positive (ER+/PR+) breast cancers that also expressed high levels of leptin had poorer prognosis than women with low leptin expression." (PMID 24176089, 2013). "The Croce group has shown that miRNAs are aberrantly expressed in human breast cancers and that this expression correlated to multiple features of cancer, including estrogen and progesterone receptor status, stage, and indices of proliferation and invasion." (PMID 23971998, 2013). "Continuous ER and PgR effects were indicated in time-to-event investigations with cohorts of breast cancer patients." (PMID 23972025, 2013). "Three studies reported that long breast-feeding was rare in patients with ER-/PgR- breast cancer, or with triple negative breast cancer." (PMID 23853760, 2013). "Increased expression of these genes also correlated with a decreased risk of breast cancer recurrence, although only four (RABEP1, PGR, SLC39A6 and FUT8) exhibited significant adjusted p-values." (PMID 23819905, 2013). "Progesterone membrane receptor component 1 (PGMRC1) is another membrane progesterone receptor, whose expression was observed in various models including breast cancer cells." (PMID 24146960, 2013). "Approximately 75% of breast cancers are estrogen and progesterone receptor (PGR)-positive and treatments to block the mitogenic activity of estrogen are a standard therapy." (PMID 23874775, 2013). "The expression of clinically significant levels of estrogen receptor-α (ERα) is seen in approximately 80% of human breast carcinomas whereas the progesterone receptor (PR) is expressed in approximately 55%." (PMID 24223121, 2013).